MDM2 (MDM2 proto-oncogene)
Diseases named in the same sentence as MDM2 in open-access papers (continued):
Sharing a sentence is not in itself a finding about the gene and the disease.
osteosarcoma (continued). "The study aimed to evaluate the effects of common variants in MDM2 and GNRH2 genes on the risk and survival of osteosarcoma in Han populations from Northwest China." (PMID 32994424, 2020). "Up to 12% of high-grade osteosarcomas have amplification of the MDM2 gene at 12q13-15, but this is higher in low-grade central osteosarcoma and parosteal osteosarcoma, with around 29% and 67–79% MDM2 amplification, respectively." (PMID 31741049, 2020). "Amplification of 12q13-15 region containing CDK4, MDM2, SAS and other potential oncogenes is present in 10% of osteosarcomas and is associated with ring chromosomes in parosteal OS." (PMID 32751922, 2020). "Despite this ability to dynamically change subcellular location, the majority of ectopically expressed Mdm2 protein can be detected in the nucleus of U2OS osteosarcoma cells." (PMID 31024344, 2019). "SJSA-1 was derived from an osteosarcoma of the femur with MDM2 proto-oncogene (MDM2) and GLI family zinc finger 1 (GLI1) gene amplification from a 19 year-old male patient." (PMID 29805751, 2018). "Idasanutlin also increased the expression of MDM2 protein in the two MDM2-amplified osteosarcoma cell lines used in this study, i.e., SJSA-1 and U-2 OS." (PMID 30352966, 2018). "TBK1 was successfully targeted in oral squamous cell carcinoma and osteosarcoma leading to a decrease in tumor activity and MDM2 amplifications are known to be involved in tumorigenesis of liposarcoma." (PMID 30006612, 2018). "The highest frequency of MDM2 amplification was observed in soft tissue tumors (20%), and osteosarcomas followed second with an incidence of 16%." (PMID 27888811, 2017). "The incidence of MDM2 gene amplification in human cancers is ~7% with soft tissue tumors, esophageal carcinomas and osteosarcoma typically having an increased frequency of MDM2 gene amplification." (PMID 29065514, 2017). "CDK4/MDM2 co-amplification was predominant in parosteal osteosarcoma, and was also present in other subtypes consistent with previous reports." (PMID 28643781, 2017).
osteosarcoma (continued). "In the present study, we investigated the resistance mechanisms for our MDM2 inhibitor SAR405838 in the SJSA-1 osteosarcoma cell line in vitro and in vivo." (PMID 26070072, 2015). "The second hotspot, located in 12q, was rearranged in four osteosarcomas (samples 1, 8, 9, 10) and coincided with the genes MDM2 and CDK4." (PMID 25300797, 2014). "Individuals carrying the mdm2 SNP309 T/G or G/G have been identified to exhibit a significantly earlier age of onset for osteosarcoma." (PMID 24520254, 2014). "We identified high levels of mdm2-C transcript in SJSA-1 osteosarcoma cells that have 25 copies of the mdm2 gene, but detected very little MDM2-C protein." (PMID 24147044, 2013). "Amplification of the MDM2 gene has been observed in a variety of human tumors and cancers, including soft tissue tumors, osteosarcoma, and esophageal carcinoma." (PMID 23638184, 2013). "A separate study described amplification of chromosome 12q13-q15 in five low-grade central osteosarcomas and amplification-related overexpression of MDM2 and CDK4 which lie within the region." (PMID 22685381, 2012). "Amplification of MDM2 (chromosome 12q15) is a relatively infrequent event in primary osteosarcoma, occurring in 3–25% of tumours but appears to be considerably more frequent in metastases and recurrences." (PMID 22685381, 2012). "Parosteal osteosarcoma is characterised by a high rate of MDM2 amplification (chromosome 12q13-q14), in up to 83% of studied tumours." (PMID 22685381, 2012). "Amplification of genes in the 12q13-15 region, such as SAS, CDK4 and MDM2, is relatively frequent in osteosarcoma, notably in low-grade parosteal OS, making them suitable as markers for distinguishing them from benign ossifying." (PMID 21106072, 2010). "Collectively, these findings demonstrate that MDM2-targeting PROTACs exert strong antitumor effects by degrading MDM2 and disrupting downstream oncogenic pathways, supporting their potential as a promising therapeutic strategy for osteosarcoma." (PMID 41827906, 2026). "Notably, MDM2 amplification has been identified in other soft tissue tumors, such as low-grade osteosarcoma and endometrial stromal sarcoma." (PMID 40826716, 2025). "Fluorescence in situ hybridization may also be of benefit as parosteal osteosarcoma is known to harbor amplification of the MDM2 gene." (PMID 39945784, 2025).
osteosarcoma (continued). "Thus, co-amplification of CDK4/MDM2 and the presence of ring chromosomes supported even stronger diagnosis of parosteal osteosarcoma." (PMID 40959149, 2025). "Therefore, MDM2 emerges as a potential novel target for differentiation therapy based on all-trans retinoic acid in osteosarcoma." (PMID 39062505, 2024). "LncRNA PCAT6 contributes to the process of osteosarcoma via enhancing MDM2 expression." (PMID 38950346, 2024). "MDM2 is amplified in 7% of soft tissue tumours, osteosarcomas, and oesophageal carcinomas." (PMID 39498386, 2024). "Moreover, some high-grade osteosarcomas can also show amplification of MDM2, which is commonly used to confirm a diagnosis of WDLPS/DDLPS." (PMID 37504306, 2023). "Moreover, among osteosarcoma patients, MDM2 overexpression correlates with metastasis and advanced stages of the disease and is often associated with more treatment-resistant tumors." (PMID 37297833, 2023). "The amplification of MDM2 on chromosome 12q15 has been detected in 16% of osteosarcomas." (PMID 37894411, 2023). "Further analysis on the differences between metastatic and non-metastatic samples revealed six intersection genes—AIM2, RPL22L1, PDPN, PKIB, GZMA, and MDM2—that related to metastasis potential of osteosarcoma and the observed gene expression differences resulted from the changes in methylation." (PMID 36072791, 2022). "MDM2 is in cancer cell types, including lung, breast, colorectal adenocarcinoma, and osteosarcoma." (PMID 36038536, 2022). "Notably, in the nine non-informative, FISH-analyzed osteosarcoma cases, there were three osteosarcoma cases with MDM2 immunohistochemical expression." (PMID 35049602, 2021). "MDM2 IHC was only positive in 27% (3/11) of the osteosarcoma cases (Cases 1–3)." (PMID 35049602, 2021). "Finally, MDM2 amplification is also a feature of intimal sarcoma and low-grade central/parosteal osteosarcoma, allowing the similar use of MDM2 and CDK4 immunohistochemistry to support their diagnosis." (PMID 33921435, 2021). "In conclusion, the three cases of high-grade OSJs that expressed MDM2 may have undergone transformation from a low-grade osteosarcoma (LGOS)." (PMID 35049602, 2021). "Their data illustrated that miR‐1244/MDM2/ circSAMD4A modulator loop may be one treatment target for osteosarcoma." (PMID 33103338, 2021). "Accumulating evidence has shown that both MDM2 and GNRH2 might be related to Osteosarcoma (OS) susceptibility." (PMID 32994424, 2020). "CDK4 and MDM2 are often co-amplified and overexpressed in osteosarcoma." (PMID 31741049, 2020). "As the percentage of CDK4 and MDM2 amplifications in low-grade central osteosarcoma and parosteal osteosarcoma are much higher than in high-grade osteosarcoma, most likely the CDK4/MDM2 amplified high-grade tumours represent progression from low grade osteosarcoma." (PMID 31741049, 2020). "Likewise MDM2 amplifications for the diagnosis of low-grade osteosarcoma, HEY1 fusions in case of mesenchymal chondrosarcoma and USP6 fusions in aneurysmal bone cyst." (PMID 31838586, 2020).
osteosarcoma (continued). "Different to HGOS, on which the following sections will focus, low-grade osteosarcoma varieties (parosteal and low-grade central) frequently harbor amplifications of the 12q13-15 amplicon, including the MDM2 and CDK4 genes, as supernumerary ring or giant chromosomes." (PMID 32295254, 2020). "The overall frequency of MDM2 gene amplification in human cancers is around 7%; however, cancer tissues such as osteosarcoma (16%), soft tissue tumors (31%), hepatocellular carcinoma (44%) and Hodgkin disease (67%) have the higher frequencies of MDM2 gene amplification." (PMID 29558908, 2018). "As the chromosome 12 CDK4/MDM2 co-amplicon is present in many different tumour types, it is conceivable that co-generation of drivers on chromosomes 5 and 17 can also be found in tumours other than osteosarcoma." (PMID 28643781, 2017). "Notably, CDKN2A,MDM2, and RB1 also appeared in the PDK1-related gene signature derived from our correlation analysis, further supporting the association between PDK1 and osteosarcoma oncogenic programs." (PMID 40971960, 2025). "In our cohort, where there was a change of diagnosis from biphenotypic sinonasal carcinoma to parosteal osteosarcoma in a head and neck case, the correct diagnosis could potentially be reached at the time of initial diagnosis by performing MDM2 FISH or immunohistochemistry." (PMID 40144205, 2025). "Furthermore, combination treatment with GSK280371 and an MDM2 inhibitor has been shown to result in increased growth inhibition and cytotoxicity in a wide range of cancer cell types, including melanoma, osteosarcoma, colon carcinoma, neuroblastoma, and breast and ovarian cancer cells." (PMID 34359777, 2021). "Here, we investigated the anticancer efficacy of two MDM2-targeting PROTAC compounds, CL0144 and CL0174, in osteosarcoma models." (PMID 41827906, 2026). "In this region are localized 2 genes, MDM2 and CDK4 which are often amplified in low-grade osteosarcomas and their proteins are found to be overexpressed." (PMID 40959149, 2025).
osteosarcoma (continued). "Regarding oncogenes, amplification of MDM2 and CDK4 is commonly observed in WDLPS, DDLPS, ALT, dedifferentiated parosteal osteosarcoma, and osteosarcoma NOS." (PMID 40141463, 2025). "Contrary, MDM2/CDK4 expression was reported rarely in conventional osteosarcoma and in primary and recurrent periosteal osteosarcomas." (PMID 40959149, 2025). "These insights are consistent with earlier findings, where MDM2 and CDK4 immunoreactivity aided in distinguishing low-grade osteosarcomas from benign fibrous dysplasia and TOS." (PMID 40926903, 2025). "In the case of an osteosarcoma and ABC-like lesions combination, testing of Ki67 and MDM2 was also performed in multinucleated cells." (PMID 40926903, 2025). "Recent therapeutic advances have identified novel MDM2 inhibitors, such as RG-7388 and Nutlin-3, which induce apoptosis in SJSA-1 osteosarcoma cells through complementary mechanisms." (PMID 41323391, 2025). "For instance, combining MDM2 inhibitors with CSF1R inhibitors reduces M2 macrophage infiltration and improves the immune microenvironment in osteosarcoma." (PMID 41323391, 2025). "When delivered via serum-derived exosomes, miR-15a is internalized by osteosarcoma (OS) cells, where it directly targets GATA-binding protein 2 (GATA2), inhibiting transcription and binding to the MDM2 promoter." (PMID 41323391, 2025). "Group C comprised seven conventional osteosarcomas displaying amplification of CDK4 and MDM2, along with numerous genome-wide copy number and structural variants." (PMID 39322633, 2024). "Group A comprised three low-grade osteosarcomas (one low-grade central and two parosteal) with amplification of CDK4 and MDM2, along with regions on chromosome arm 12p." (PMID 39322633, 2024). "We selected osteosarcomas based on subtype or CDK4 and MDM2 status, drawing cases from two distinct cohorts." (PMID 39322633, 2024). "The authors found that all of the parosteal osteosarcoma samples demonstrated positivity to CDK4 gene amplification, and the majority showed positivity to MDM2 gene amplification." (PMID 38057715, 2023). "Positive staining with antibodies against MDM2 and CDK4 have also shown to be helpful in distinguishing low-grade osteosarcoma from benign fibro-osseous mimics but should be used with caution due to limited specificity." (PMID 35875137, 2022). "In particular, CNV was more frequent in CCND3, AURKB, CCNE1, GID4, and MYC in P-AYA, while MDM2, CDKN2A/B, and FRS2 were more frequently altered in adult osteosarcoma (p < 0.001)." (PMID 35705558, 2022). "Regarding its potential role in bone, high levels of MDM2 in mice osteoblast and in the MG63 human osteosarcoma cell lines induced an increase in bone mineralization and also corrected aged-related bone loss in mice." (PMID 35742976, 2022).